Y_RNA (Y RNA )
Gene: Miscellaneous RNA gene on chromosome 1 (44,153,385 to 44,153,480, reverse strand). Ensembl gene ENSG00000200171.
Homologues: Orthologues: chimpanzee Y_RNA (99% identical), macaque Y_RNA (99% identical), rabbit Y_RNA (92% identical), dog Y_RNA (91% identical), guinea pig Y_RNA (91% identical), rabbit Y_RNA (91% identical), rabbit Y_RNA (90% identical), rabbit Y_RNA (89% identical). Paralogues in human: RNY4 (92% identical), RNY4P6 (91% identical), RNY4P13 (86% identical), RNY4P19 (86% identical), RNY4P7 (86% identical), Y_RNA (86% identical), RNY4P10 (85% identical), RNY4P17 (85% identical), RNY4P25 (85% identical), RNY4P3 (85% identical), Y_RNA (85% identical), RNY4P14 (84% identical), and 90 more.